Y_RNA (Y RNA )
Gene: Miscellaneous RNA gene on chromosome 3 (27,547,757 to 27,547,858, reverse strand). Ensembl gene ENSG00000238912.
Homologues: Orthologues: chimpanzee Y_RNA (99% identical), macaque Y_RNA (96% identical). Paralogues in human: Y_RNA (91% identical), Y_RNA (90% identical), RNY3 (89% identical), Y_RNA (89% identical), Y_RNA (88% identical), RNY3P1 (87% identical), RNY3P2 (87% identical), Y_RNA (87% identical), RNY3P16 (86% identical), Y_RNA (86% identical), Y_RNA (85% identical), RNY3P3 (84% identical), and 96 more.